SERPINB12 (serpin family B member 12)
Description:
Inhibits trypsin and plasmin, but not thrombin, coagulation factor Xa, or urokinase-type plasminogen activator. May play a role in cell differentiation.
Synonyms: YUKOPIN
Tractability: Antibody: its Gene Ontology location is reachable by antibodies, with high confidence.
Gene: Protein-coding gene on chromosome 18 (63,542,369 to 63,569,329, forward strand). Ensembl gene ENSG00000166634.
Subcellular location: Cytoplasm
Pathways (Reactome):
Immune System: Neutrophil degranulation
Gene Ontology:
Molecular function: serine-type endopeptidase inhibitor activity; enzyme binding
Biological process: negative regulation of protein catabolic process
Cellular component: extracellular matrix; cytoplasm; ficolin-1-rich granule membrane; plasma membrane; cornified envelope
Genetic constraint (gnomAD): Loss-of-function variants: 51 observed, 35.79 expected, observed/expected ratio (o/e) 1.42, 90% interval 1.14 to 1.79. The upper end of that interval is the gene's LOEUF score, 1.79, which puts it in group 6 of 6, group 1 being the genes least tolerant of losing a copy. Missense variants: 493 observed, 480.83 expected, observed/expected ratio (o/e) 1.03, 90% interval 0.95 to 1.11. Synonymous variants: 167 observed, 176.09 expected, observed/expected ratio (o/e) 0.95, 90% interval 0.83 to 1.08.
Homologues: Orthologues: chimpanzee SERPINB12 (99% identical), macaque SERPINB12 (95% identical), chimpanzee SERPINB12 (95% identical), pig SERPINB12 (81% identical), dog SERPINB12 (80% identical), guinea pig SERPINB12 (75% identical), rabbit SERPINB12 (75% identical), rat Serpinb12 (72% identical), mouse Serpinb12 (72% identical). Paralogues in human: SERPINB4 (45% identical), SERPINB3 (44% identical), SERPINB11 (40% identical), SERPINB13 (40% identical), SERPINB10 (39% identical), SERPINB1 (39% identical), SERPINB6 (38% identical), SERPINB2 (37% identical), SERPINB8 (37% identical), SERPINB9 (36% identical), SERPINB7 (36% identical), SERPINC1 (33% identical), and 24 more.
Diseases named in the same sentence as SERPINB12 in open-access papers:
SERPINB12 is named in the same sentence as 18 diseases in open-access papers, as found by Europe PMC text mining. Sharing a sentence is not in itself a finding about the gene and the disease. The quoted sentences say what the papers report.
ovarian carcinoma (3 papers, 2014 to 2024). A malignant neoplasm originating from the surface ovarian epithelium. "In addition, SERPINB12 is clearly associated with and may be an essential regulatory factor in abnormal growth and dysfunction of ovarian carcinomas." (PMID 25020046, 2014). "Results of the present study indicate that expression of SERPINB12 mRNA increased about 206-fold (P<0.001) only in ovarian carcinoma of laying hens." (PMID 25020046, 2014). "Another article has reported that SERPINB12 maybe related to the abnormal growth and dysfunction of ovarian cancer." (PMID 34194476, 2021). "Furthermore, SERPINB12 mRNA and protein increase significantly in GE of cancerous ovaries of laying hens with epithelia-derived ovarian cancer." (PMID 25020046, 2014). "Additionally, animal studies suggest that Serpinb12 has the potential to serve as a biomarker and may be employed for the early detection of ovarian cancer in women." (PMID 38539447, 2024). "Collectively, these results indicate that SERPINB12 is a novel estrogen-stimulated gene that is up-regulated by estrogen in epithelial cells of the chicken oviduct and that it is a potential biomarker for early detection of ovarian carcinomas in laying hens and women." (PMID 25020046, 2014).
meningitis (2 papers, 2022 to 2025). A disorder characterized by acute inflammation of the meninges of the brain and/or spinal cord. "Three SERPINs different from the SERPINB12, found in saliva, had increased relative abundance in serum of pigs with meningitis (LOC106504547, LOC396684, and LOC100156325)." (PMID 36430174, 2022).
atopic dermatitis (1 paper, 2024). "SerpinB12 is a gene associated with epidermal permeability barrier, and its expression is decreased in atopic dermatitis model mice." (PMID 39737188, 2024). "However, it is unclear whether SerpinB12 is a key molecule and specific mechanism that regulates impaired epidermal barrier function in atopic dermatitis, and further research is needed." (PMID 39737188, 2024).
cystic fibrosis (1 paper, 2025). Autosomal recessive disorder caused by pathogenic variants in the CFTR gene (cystic fibrosis transmembrane conductance regulator), which encodes a chloride and bicarbonate channel expressed in epithelial cells, and follow the diagnosis criteria. "These proteins included Serpin Family B Member 12 (SERPINB12), and fibrillin-1 (FBN1), proteins associated with cystic fibrosis and connective tissue disease." (PMID 40508199, 2025).
eosinophilic esophagitis (1 paper, 2025). Eosinophilic esophagitis (EoE) is a chronic, allergic disease of the esophagus characterized clinically by symptoms of esophageal dysfunction (including vomiting, dysphagia, feeding disorders, food impaction and abdominal pain) which persist after treatment with proton pump inhibitors (PPIs). "Downregulated SERPINB12 compromises protease regulation and barrier integrity, akin to inflammatory relapse in eosinophilic esophagitis." (PMID 41516009, 2025).
lung carcinoma (1 paper, 2024). "We also noted that SERPINB12 expression was upregulated at stage I patients, comparable to stage II and III, which means the up-regulation of SERPINB12 occurred in the early stages of tumor progression and may serve as an indicator for early screening of lung cancer." (PMID 38504347, 2024).
tumor (4 papers, 2022 to 2024). "Moreover, downregulation of SERPINB12 attenuated Wnt signaling by inhibiting the nuclear translocation of β-catenin, which explained the molecular mechanism underlying tumor progression." (PMID 38504347, 2024). "SERPINB12 was upregulated in tumor tissues compared with that in normal tissues, and it was also significantly overexpressed in smokers." (PMID 38504347, 2024). "The results illustrated that tumor growth was dramatically impaired after SERPINB12 silencing, as clarified by the tumor weight." (PMID 38504347, 2024). "In addition, the expression of Ki-67 in the SERPINB12 knockdown groups was much lower than that in the control group, which indicated that downregulation of SERPINB12 reduced tumor growth." (PMID 38504347, 2024). "In addition, we also measured the expression of SERPINB12 in tumor and adjacent tumor tissues using our samples collected in Shidong Hospital of Yangpu District, which indicated that SERPINB12 was elevated in tumor tissues." (PMID 38504347, 2024). "Furthermore, we preliminarily explored the molecular mechanism of SERPINB12 in promoting tumor progression." (PMID 38504347, 2024). "Moreover, we further verified the function of SERPINB12 in tumor growth in vivo." (PMID 38504347, 2024). "SERPINB12 could facilitate the EMT process to promote tumor metastasis." (PMID 38504347, 2024). "Further analysis of the shared 61 proteins revealed that there were a large number of tumor-related proteins, such as HSPA5, HNRNPH1, HSPA8, TGM3, and SERPINB12." (PMID 37715221, 2023).
cancer (2 papers, 2022 to 2024). A tumor composed of atypical neoplastic, often pleomorphic cells that invade other tissues. "SERPINB12 is a kind of serpin peptidase inhibitor, but its function in malignant tumors remains largely unknown." (PMID 38504347, 2024). "SERPINB12 expression was upregulated in cancer cells compared with that in normal lung cells." (PMID 38504347, 2024). "SERPINB12 is a member of the SERPINB family, but its function in cancer is unknown." (PMID 38504347, 2024).
SERPINB12 also shares sentences with these, for which no sentence is quoted: Sepsis (3 papers); acute coronary syndrome (1); bacterial infection (1); breast tumors (1); connective tissue disease (1); familial partial lipodystrophy (1); hair diseases (1); invasive carcinoma (1); lung adenocarcinoma (1); scleroderma (1).